VESTAR (VEGFC mRNA stability associated lncRNA)
Synonyms: MGC23270; LINC00638
Gene: Long non-coding RNA gene on chromosome 14 (104,821,201 to 104,823,718, forward strand). Ensembl gene ENSG00000258701.
Diseases named in the same sentence as VESTAR in open-access papers:
VESTAR is named in the same sentence as 5 diseases in open-access papers, as found by Europe PMC text mining. Sharing a sentence is not in itself a finding about the gene and the disease.
VESTAR shares sentences with these, for which no sentence is quoted: cancer (1 paper); gastric cancer (1); hepatocellular carcinoma (1); rheumatoid arthritis (1); tumor (1).